DHX32 (DEAH-box helicase 32 (putative))
Synonyms: DHLP1; DDX32; FLJ10889; FLJ10694
Tractability: PROTAC: ubiquitination databases record sites on it; its protein half-life has been measured.
Target class: Enzyme; Hydrolase
Gene: Protein-coding gene on chromosome 10 (125,836,337 to 125,896,514, reverse strand). Ensembl gene ENSG00000089876.
Subcellular location: Nucleus; Mitochondrion
Gene Ontology:
Molecular function: protein binding; helicase activity; ATP hydrolysis activity; RNA helicase activity
Cellular component: mitochondrion; spliceosomal complex; nucleus
Genetic constraint (gnomAD): Loss-of-function variants: 56 observed, 76.16 expected, observed/expected ratio (o/e) 0.74, 90% interval 0.59 to 0.92. The upper end of that interval is the gene's LOEUF score, 0.92, which puts it in group 3 of 6, group 1 being the genes least tolerant of losing a copy. Missense variants: 762 observed, 932.15 expected, observed/expected ratio (o/e) 0.82, 90% interval 0.77 to 0.87. Synonymous variants: 310 observed, 332.2 expected, observed/expected ratio (o/e) 0.93, 90% interval 0.85 to 1.02.
Homologues: Orthologues: chimpanzee DHX32 (99% identical), macaque DHX32 (97% identical), dog DHX32 (92% identical), pig DHX32 (89% identical), mouse Dhx32 (88% identical), guinea pig DHX32 (88% identical), rat Dhx32 (88% identical), rabbit DHX32 (81% identical), tropical clawed frog dhx32 (62% identical), zebrafish dhx32b (54% identical), zebrafish dhx32a (51% identical). Paralogues in human: DQX1 (42% identical), DHX15 (37% identical), DHX8 (32% identical), DHX34 (29% identical), DHX16 (29% identical), DHX35 (29% identical), DHX38 (28% identical), DHX57 (24% identical), DHX33 (24% identical), DHX40 (24% identical), DHX29 (23% identical), DHX37 (23% identical), and 6 more.
Diseases named in the same sentence as DHX32 in open-access papers:
DHX32 is named in the same sentence as 11 diseases in open-access papers, as found by Europe PMC text mining. Sharing a sentence is not in itself a finding about the gene and the disease. The quoted sentences say what the papers report.
colorectal cancer (4 papers, 2009 to 2021). A primary or metastatic malignant neoplasm that affects the colon or rectum. "The results are in accordance with our previous report that the upregulated expression of DHX32 in colorectal cancer tissues is associated with lymph gland metastasis." (PMID 25782664, 2015). "In our study, we found that DHX32 was overexpressed in colorectal cancer compared with the adjacent normal tissues, suggesting that abnormal expression of DHX32 is associated with the development of colorectal cancer." (PMID 19161603, 2009). "Our results suggested that the level of DHX32 gene expression in colorectal cancer was significantly associated with cancer location, lymph gland metastasis, cancer nodal status, differentiation grade and Dukes' stage." (PMID 19161603, 2009). "Our results indicated that the differential expression of DHX32 in colorectal carcinoma was significantly associated with tumor location, lymph gland metastasis, tumor nodal status, differentiation grade, and Dukes' stage." (PMID 19161603, 2009). "In addition, we found that the level of DHX32 gene expression in colorectal cancer was significantly associated with cancer location, lymph gland metastasis, cancer nodal status, differentiation grade, and Dukes, stage." (PMID 19161603, 2009). "Furthermore, our results suggested that the level of DHX32 gene expression in colorectal carcinoma was significantly associated with tumor location, lymph gland metastasis, tumor nodal status, differentiation grade, and Dukes' stage." (PMID 19161603, 2009). "The expression of DHX32 was significantly related to clinically pathological features of colorectal cancer, and can be served as a prognostic biomarker for colorectal cancer patients." (PMID 33729094, 2021). "DEAH-box polypeptide 32 (DHX32, also known as DDX32) is a new member of the DEAH box helicase family and overexpressed DHX32 was observed in several kinds of solid tumours, including colorectal cancer and breast cancer." (PMID 33729094, 2021). "The expression of DHX32 was upregulated in colorectal cancer (CRC) tissues and remarkably related to local or lymphatic metastasis, differentiation grade, and Dukes’ stage in CRC patients." (PMID 33729094, 2021). "It was reported that DHX32 overexpression promoted the proliferation and mobility of colorectal cancer cells and augmented β-catenin signaling to enhance angiogenesis in colorectal cancer." (PMID 33729094, 2021). "Consistent with our previous report in human colorectal cancer samples, expression of DHX32 at both the mRNA and protein levels was higher in human CRC cells than in normal human colonic epithelial cells." (PMID 25782664, 2015). "Our previous work demonstrates that DHX32 is upregulated in colorectal cancer (CRC) compared to its adjacent normal tissues." (PMID 25782664, 2015). "In this study, we found that DHX32, a novel RNA helicase, was significantly up-regulated in colorectal cancer compared to its adjacent normal tissue using a combination of DD-PCR and real-time PCR methods." (PMID 19161603, 2009). "In this study, we demonstrated that human DHX32, a novel RNA helicase, was up-regulated in colorectal cancer compared to its adjacent normal tissues." (PMID 19161603, 2009). "We identified by DD-PCR a novel RNA helicase, DHX32, which showed higher expression in colorectal cancer tissues than their adjacent tissues, and this result was confirmed by real time RT-PCR." (PMID 19161603, 2009). "It still remains to be further investigated for the functions of DHX32 during the progression of colorectal cancer." (PMID 19161603, 2009). "DHX32 may also serve as a bio-marker for judging the levels of malignancy of colorectal cancer, which may guide the development of anticancer therapy regime after additional studies." (PMID 19161603, 2009). "DHX32 may play an important role in the development of colorectal cancer and could serve as a novel biomarker for colorectal cancer after additional investigation." (PMID 19161603, 2009).
colorectal cancer (continued). "DHX32 may play an important role in the development of colorectal cancer and additional studies may help use DHX32 as a novel biomarker for colorectal cancer." (PMID 19161603, 2009).
breast carcinoma (2 papers, 2021 to 2024). "DHX32 expression has been associated with a poor prognosis in human breast cancer patients." (PMID 38951817, 2024). "Moreover, high level of DHX32 expression also predicted poor prognosis in breast cancer patients." (PMID 33729094, 2021). "Moreover, DHX32 expression was demonstrated to be negatively correlated with overall survival and disease-free survival in breast cancer patients and could serve as a potential therapeutic target." (PMID 33729094, 2021).
colon cancer (2 papers, 2009 to 2015). "The equivalence of RPL32 and KRT20 as well as the downstream relation of TFDP1 and DHX32 to these two genes is a first step toward refining the architecture of the colon cancer invasiveness network." (PMID 19180177, 2009). "In this study, we reported that DHX32 was overexpressed in human colon cancer cells." (PMID 25782664, 2015).
acute lymphoblastic leukaemia (1 paper, 2021). "However, DHX32 was downregulated in acute lymphoblastic leukaemia and might regulate lymphopoiesis." (PMID 33729094, 2021).
colorectal tumors (1 paper, 2009). "We compared both positive rate and gene expression level in order to confirm the difference of DHX32 gene expression between colorectal tumors and their adjacent normal tissues." (PMID 19161603, 2009). "We found that the positive rate of DHX32 gene expression was significantly higher in the colorectal tumors (76.5%) than that in the adjacent normal tissues (26.4%)." (PMID 19161603, 2009). "Consistent with the higher positive rate of DHX32 gene expression in the colorectal tumors, its gene expression level was also significantly higher than that in the adjacent normal tissues." (PMID 19161603, 2009).
giant cell tumor (1 paper, 2020). A benign, intermediate, or malignant tumor that arises from the bone or soft tissue. "One of the main regulators of lnc-DHX32-2:1, which targeted for gene ADAM12, has been implicated in a variety of biological processes, including lung cancer and the development of giant cell tumors, and positively involved in the regulation of the MAPK/ERK pathway." (PMID 33519900, 2020).
kidney tumors (1 paper, 2009). "DHX32 was reported as anti-sense to another gene, BCCIP (BRCA2 and CDKN1A Interacting Protein), and BCCIP was down-regulated in kidney tumors." (PMID 19161603, 2009).
cancer (4 papers, 2009 to 2022). A tumor composed of atypical neoplastic, often pleomorphic cells that invade other tissues. "To date, however, although several reports have shown that DHX32 contributes to cancer development, the molecular mechanism underlying the oncogenic activities of DHX32 are still elusive." (PMID 25782664, 2015). "So far, several groups have attempted to reveal the underlying mechanisms by which DHX32 involves in cancer development, but the exact biochemical activities and biological functions of DHX32 are still elusive." (PMID 19161603, 2009). "Overexpressed DHX32 promoted SW480 cancer cells proliferation, migration, and invasion, as well as decreased the susceptibility to chemotherapy agent 5-Fluorouracil." (PMID 25782664, 2015). "DHX32 was reported to function as either a cancer-promoting or a tumour-suppressive gene depending on tumour types, which indicated that the regulation of DHX32 in tumour development might be complex." (PMID 33729094, 2021). "The correlation between DHX32 and cancer progression has been explored in several kinds of cancers." (PMID 33729094, 2021). "The involvement of DHX32 in other cancer development was previously demonstrated by other groups." (PMID 19161603, 2009). "In LIHC, DHX9, DHX32, and DHX15 play important roles in promoting cancer cell motility and proliferation, inhibiting cell apoptosis, and indicating a poor prognosis." (PMID 35814441, 2022). "In conclusion, this is the first report demonstrating that DHX32 promotes cell proliferation, migration, and invasion, as well as reduces sensitivity to chemotherapy reagents in CRC, via modulating expressions of gene involved in cancer cell growth, migration, and survival." (PMID 25782664, 2015).
tumor (3 papers, 2009 to 2021). "In our in vivo study, we observed that inhibition of DHX32 suppressed HCC tumour growth." (PMID 33729094, 2021). "Therefore, our in vivo study indicates that suppression of DHX32 blocks HCC tumour growth." (PMID 33729094, 2021). "Silencing DHX32 reversed EMT, inhibited the malignancy behaviors of HCC cells, and suppressed tumour growth." (PMID 33729094, 2021). "DHX32 expression was upregulated in human HCC cells and ectopic expression of DHX32 induced EMT, promoted the mobility and proliferation of HCC cells, and enhanced tumour growth in vivo." (PMID 33729094, 2021). "Moreover, to further confirm the effect of DHX32/β-catenin pathway on HCC proliferation and EMT in vivo, we should also detect the expression of proliferation makers, such as PCNA, Cyclin D1, β-catenin expression, and EMT markers including E-cadherin and vimentin in the tumour tissues." (PMID 33729094, 2021).
hematological diseases (1 paper, 2023). "Recent studies have reported the role of several DHX9-like genes including DDX41, DDX3X, and DHX32 in hematological diseases." (PMID 37305700, 2023).
DHX32 also shares sentences with these, for which no sentence is quoted: lung carcinoma (1 paper).